HIF1A (hypoxia inducible factor 1 subunit alpha)
Diseases named in the same sentence as HIF1A in open-access papers (continued):
Sharing a sentence is not in itself a finding about the gene and the disease.
cancer (continued). "Upregulation of HIF-1α/miR-210-3p and downregulation of RGMA in OSCC is known as a mechanism for the proliferation, invasion, and migration of cancer cells." (PMID 37221555, 2023). "This revealed that HIF1α and MYC were significantly repressed in dormant as compared to the proliferating cancer cells." (PMID 37456245, 2023). "Henceforth, HIF-1α, through direct regulation of PDK1, LDHA, and MCT-4, effectively saves cancer cells from acidosis and harmful reactive oxygen species." (PMID 36891273, 2023). "The expression of HIF-1α and HIF-2α is important in regulating the expression of VE-cadherin and modulating VM in various cancer types." (PMID 37298296, 2023). "LIPH catalyzes the conversion of PA to LPA and facilitates cancer cell proliferation by enhancing YAP1 nuclear localization, stimulating the PI3K/AKT/HIF1A pathway, and maintaining ALDOA stability, ultimately resulting in aberrant glycolysis and tumorigenesis." (PMID 37990271, 2023). "Although HIF-1α and HIF-2α share common target genes, each has unique target genes and is known to play independent roles in different cancer types." (PMID 36901857, 2023). "Therefore, blocking the function of HIF-1α may be beneficial for inhibiting cancer progression." (PMID 38052785, 2023). "HIF1α transcriptionally activates the lncRNA N-Myc downstream regulated 1-overlapping 1 (NDRG1-OT1) in breast cancer cells, which aids in cancer progression by destabilizing its parent gene NDRG1 both at transcriptional and post-translational levels." (PMID 37583933, 2023). "NOX2-dependent ROS generation induces the activation of HIF1α and thereby stimulates HIF-related cancer events." (PMID 36768405, 2023). "The loss of function of VHL leads to a constitutive stabilization of HIF-1α and HIF-2α, which induces the activation of HIF-target genes and pathways involved in cancer progression." (PMID 37443821, 2023). "Direct or indirect targeting of HIF-1α and/or HIF-2α is an important therapeutic strategy for patients with anemia and different types of cancers." (PMID 37201586, 2023). "Finally, we found that HIF-1A signaling might result in the silencing of PUS10 in cancer." (PMID 37596681, 2023). "Its effect is limited because its role as an HIF-1α activator requires the expression of membrane type-1 matrix metalloproteinase (MT1-MMP), which is limited to specific cells, such as macrophages, cancer cells, and fibroblasts." (PMID 36831085, 2023). "Overall, Mint3 requires the coordinated expression of MT1-MMP to activate HIF-1α; therefore, the critical influence of Mint3 activity is restricted to loci with sufficient levels of MT1-MMP expression, such as in macrophages, cancer cells, and fibroblasts." (PMID 36831085, 2023). "HIF-1α is closely related to aerobic glycolysis in cancer, mainly by regulating HK2 and GLUT1 to participate in cancer cell metabolism and accelerate the Warburg effect." (PMID 37204526, 2023). "Huaier has been verified to have anti-cancer effects by inhibiting cancer cell growth and energy metabolism through the PI3K/AKT/HIF-1α pathway." (PMID 37251326, 2023). "Metformin has shown promising effects in different cancers and has been shown to regulate metabolism by interacting with AMPK, the PI3K-AKT-mTOR axis, and HIF-1α." (PMID 36768924, 2023). "These drugs treat cancer by inhibiting the angiogenesis triggers, including the vascular endothelial growth factor (VEGF) and hypoxia-inducible factor 1-α (HIF-1α) release." (PMID 36984763, 2023). "For instance, miR-153 inhibits angiogenesis in breast cancer tissues by directly targeting HIF1α and angiopoietin (ANG1), thereby suppressing the migration and invasion of cancer cells." (PMID 37583933, 2023). "Inhibiting MEK decreased HIF-1α expression and FECH activity and increased 5-ALA-induced PpIX accumulation in cancers." (PMID 36768924, 2023).
cancer (continued). "In cancer cells and cardiomyocytes of group 2 PH, PKM2 is also a transcriptional co-activator for HIF-1α, constituting a positive feedback loop that favors a reliance on glycolysis." (PMID 36819102, 2023). "Activation of HIF-1α by this immune checkpoint regulates glycolysis in OSCC and increases glucose uptake by cancer cells." (PMID 37221555, 2023). "Hypoxia-inducible factor 1 alpha (HIF1α) exhibits crucial roles in regulation of energy metabolism, angiogenesis and other processes in the TME and provides cancer cells to gain more proliferation and metastasis capacity." (PMID 36835352, 2023). "Cancer-promoting levels of NO were found at concentrations of 100 to 500 nM, which led to the activation of pathways involving RAS/ERK, PI3K/Akt/b-catenin, HIF-1α, NrF2, and TGFb." (PMID 37958916, 2023). "Expression of PD-L1 in cancer cells is regulated by multiple signaling pathways, including transcription factors, such as STAT3, HIF1α and MYC." (PMID 37928424, 2023). "Meanwhile, hyperglycemia can regulate the stability and function of HIF-1α by interfering with its degradation by PHD enzymes, leading to enhancement of its anti-apoptotic properties in cancer cells." (PMID 36672448, 2023). "It triggers H2O2 catabolism to generate O2 to alleviate cancer hypoxia, enhance PDT and radiotherapy sensitivity, promote TAM polarization from the M2 to the M1 phenotype, and inhibit HIF-1α expression." (PMID 36797231, 2023). "In this review, we provide an overview of the interactions and collaborations of SP1, HIF1A, and MYC in the regulation of various cancer-related genes, and their potential implications in the development of anticancer therapy." (PMID 37998757, 2023). "Mounting evidence confirmed that several potential candidates were overexpressed in certain cancers and contributed to glycolysis, including FUBP1, HIF-1α, and CD47." (PMID 37626036, 2023). "For instance, NOX1-induced HIF1α specifically increases multidrug resistance gene 1 (MDR1) expression, which counteracts excess ROS and leads to cancer cells’ enhanced expression of P-gp and drug resistance." (PMID 37563639, 2023). "In conclusion, UEC and OCC showed high HIF-1α, STAT3, and PSMA expression, indicating that both cancer types share developmental and progression pathways." (PMID 37713813, 2023). "Cancer cells cocultured with adipocytes increase the levels of EMT-inducing transcription factors FOXC2 and TWIST1 in a HIF-1α adipocyte expression-dependent manner." (PMID 36670988, 2023). "Here, we determined that the downregulation of PUS10 is at least partially induced by HIF-1A by transcriptional inhibition, thus providing another link between hypoxia and RCC cancer metastasis." (PMID 37596681, 2023). "The blocking of IL-6 in the interaction of HIF-1α-expressed HCC cells and NK cells enhanced the NK cytotoxicity to cancer cells and the expression of activating receptors on NK cells." (PMID 37501379, 2023). "Their experiments revealed that experimentally overexpressed SESN2 inhibits HIF-1α accumulation in colon cancer cell lines HCT116 and HT29 exposed to hypoxic condition and prevents cancer cell metastasis." (PMID 37284849, 2023). "Hypoxia is frequently present in the TME in solid tumors; it induces HIF-driven transcriptional responses in cancer cells, where a direct link between PDL-1 and HIF-1α has been reported." (PMID 37626660, 2023). "These signals promote the stabilization of HIF-1α; subsequent HIF transcriptional activity leads to the expression of multiple genes that contribute to cancer cell survival, altered metabolism, migration, and metastatic phenotype." (PMID 36935009, 2023). "Both HIF-1α and HIF-2α are known to activate factors involved in pluripotency and regulate the stem cell phenotype, both in normal and cancer cells." (PMID 36982940, 2023).
cancer (continued). "HIF is crucially involved in the progression of tumors, and the upregulation of HIF-1α and HIF-2α has been proved to indicate an unfavorable prognosis in numerous cancer patients." (PMID 38085375, 2023). "UBE2O progressively promotes cancer growth and progression via upregulating AMPK/mTORC1, which induces HIF1α, completing a positive feedback loop to confer a continuous hypoxic environment favoring cancer cell progression and stemness." (PMID 37583933, 2023). "In different cancer cell lines, fucoidans were able to inhibit the expression of the two key angiogenesis regulators VEGF and HIF-1α." (PMID 37233501, 2023). "Such fluctuations alter the energy status of cancer cells and interfere with signaling pathways (AMPK, mTOR), transcription factors (hypoxia-inducible factor 1 alpha; HIF1α), and proteins (glucose transporter; GLUT) known to be associated with PGC-1α activity." (PMID 37237941, 2023). "CD34+KIT low stem cells for GIST, cancer cell quiescence, and altering the metabolic phenotype of GIST through reactive oxygen species (ROS0 and hypoxia-inducible factor-1α (HIF-1α) can play a role 54–56." (PMID 37545902, 2023). "As a novel type of lncRNA, cytoplasmic lncRNA LINK- An is widely distributed in the cytoplasm of various cancers and promotes the reprogramming of TNBC glycolysis by relying on the HIF-1α signaling pathway, highlighting the important role of lncRNA in tumors." (PMID 37204526, 2023). "This study provides evidence for the anti-cancer potential of BP-LCN formulation against NSCLC by decreasing the levels of survivin and hif-1α and increasing the levels of p27KIP1." (PMID 37534226, 2023). "Melatonin regulated the protein expressions of the HIF-1α and Bcl2 pathways’ downstream proteins, including MCL1, Bcl-XL, Bax, claspin, and survivin, which possess anti-cancer effects in numerous cancer cell types." (PMID 37086261, 2023). "Curcumin decreased the high glucose-induced survival of cancer cells upon doxorubicin and methotrexate treatment, suppressed glucose uptake, lactate production, expression of GLUT1/3, MCT1/4, HIF1α, mTOR, STAT3, and multidrug resistance protein MDR-1." (PMID 38001865, 2023). "Combining polydatin, a natural precursor of resveratrol, with 2-DG in MCF-7 and 4T1 breast cell lines can stimulate cancer cell apoptosis and restrict cell proliferation by inhibiting the ROS/PI3K/AKT/HIF-1α/ hexokinase 2 signaling axis." (PMID 37460927, 2023). "Although further studies are required, it is warranted to investigate the anti-cancer value of drugs targeting MDM2 and/or HIF-1α in RB or even other solid tumor types." (PMID 36741966, 2023). "The hypoxia-inducible factor-1 (HIF-1), composed of two subunits, HIF-1α and HIF-1β, potentially mediates cancer angiogenesis, metabolism, and metastasis, enhancing cancer survival and progression." (PMID 37564184, 2023). "Moreover, leptin may drive cancer progression in a hypoxic environment and when mitochondrial respiration is impaired by sustaining aerobic glycolysis, which can stimulate cancer survival in an adverse metabolic microenvironment by sustaining HIF-1α activity." (PMID 37686525, 2023). "Accordingly, HIF1α and MYC-dependent genes were differentially expressed between dormant and proliferating cancer cell samples." (PMID 37456245, 2023). "It has been shown that HIF-1α, AMPK, and ROS are involved in preserving the oxidative state of the cancer cells while the Warburg pathway is running in the background." (PMID 37762231, 2023). "Although Mint3 is ubiquitously expressed, its effect on HIF-1α regulation is limited to specific regions where MT1-MMP is expressed simultaneously, such as fibroblasts, macrophages, and cancer cells." (PMID 36831085, 2023).
cancer (continued). "In the upstream, CD147 regulates the expression HIF-1α and HIF-2α, thus one of the “main switches” of angiogenesis, hypoxic and metabolic rewiring of cancers." (PMID 38023152, 2023). "During hypoxia, HIF1α, NRF2, and KEAP1 are activated, which has aberrant consequences for cancer cells." (PMID 36769044, 2023). "Mechanistically, it sponges off miR-487a from mRNAs of HIF1α, which results in HIF1α mediated transcription of hexokinase II (HK2) and promotes glycolysis and proliferation in cancer cells." (PMID 37583933, 2023). "During cancer metastasis, YB1 enhances HIF1a protein expression by directly binding to and activating translation of HIF1a message RNA." (PMID 37035211, 2023). "The HIF-1, formed by dimerization of the HIF-1α with HIF-1β, is the leading HIF type in cancer cells." (PMID 36846589, 2023). "It is well established that increased protein synthesis and decreased protein degradation lead to increased HIF-1α and HIF-2α protein levels in many cancers." (PMID 36831670, 2023). "The proliferation of cancer cells was arrested at the S-phase cell cycle, and the migration of cancer cells was inhibited by the increasing concentration of curcumin, together with the decreasing expressions of STAT3, VEGF, and HIF-1α signaling pathways." (PMID 37333486, 2023). "Noticeably, our study is the first report the role of HDAC5 in the regulation of p16INK4a expression in GC cells, thus providing a novel HDAC5-mediated pathway in cancer, in addition to the TAp63/maspin, HIPK2/HIF1α, and p65/NF-κB pathways." (PMID 37415735, 2023). "Cancer cells treated with DMEM or MEM were used to determine the effect of DMEM containing high levels of glucose and pyruvate on the stability of HIF-1α under conditions of hypoxia." (PMID 37777750, 2023). "In particular, HIF1A and EPAS1/HIF2A can have opposing effects in cancer cells by controlling the transcription of different target genes." (PMID 38276269, 2023). "During cancer progression, EPA can decrease expression of important proteins such as HIF-1α and VEGF, which are very important in the metastasis process and stimulate apoptosis by caspase activation." (PMID 37367643, 2023). "Anthracyclines, widely used chemotherapeutics in cancer, inhibit HIF-1α action by impairing the binding of HIF-1α to DNA." (PMID 36846589, 2023). "HIF1α also induces lncRNA induced by hypoxia and abundant in TNBC (lncIHAT) expression to promote cancer cell survival and lung metastasis in vivo." (PMID 37583933, 2023). "We also sought to determine the anti-cancer mechanism of IDF-11774, which involves cell cycle arrest and apoptosis followed by HIF-1α downregulation." (PMID 38140111, 2023). "Collectively, our findings identified the Rap druggable biomarkers of mTORC1/HIF-1α signalers and MCT4 lactate exporter as the most plausible anti-cancer therapeutic targets for reversing nutritional FD-potentiated lactate disorders and LCS metastases." (PMID 36986244, 2023). "To explore the roles of circ_ZNF778_006/ miR-18b-5p/HIF-1α axis in the cancer progression of ESCC cells, first we constructed TE-1 cells with HIF-1α-siRNAs by transfecting with different HIF-1α siRNAs." (PMID 37938614, 2023). "HIF-1a can induce a hypoxic microenvironment in OC, and when the expression level of HIF-1a is elevated, it facilitates the cells to make full use of the oxygen when they are hypoxic, confirming that TME favors metabolic reprogramming in cancer." (PMID 38090580, 2023). "For FAP, significantly positive Pearson correlations coefficients for most cancer entities were found with prominent angiogenesis-related genes FLT1 (also known as VEGFR1), KDR (also known as VEGFR2), HIF1A, and ETS1." (PMID 36672341, 2023). "Lastly, HIF-1α was upregulated in the ferroptotic microglia in the tri-culture, and BAY 87–2243 is a HIF-1α inhibitor in phase 1 clinical trials for cancer." (PMID 36536241, 2023).
cancer (continued). "HIF-1 is a heterodimer composed of HIF-1α and HIF-1β subunits, and because of its crucial role in tumor angiogenesis, it has been recognized as an important cancer drug target." (PMID 35683032, 2022). "This information is consistent with our findings which show that HIF-1α positively regulates YY1 expression, and that several transcription factors are reportedly involved in chemoresistance of different types of cancer including ALL." (PMID 35163649, 2022). "HIF-1α and HIF-2α regulate a number of physiological pathways involved in cancer, such as cell proliferation, survival, apoptosis, angiogenesis, glucose metabolism, immune cell activation and stem cells." (PMID 35629169, 2022). "Several studies have reported that p300/CBP acetylates HIF-1α at K709 and suppresses the polyubiquitination and degradation of HIF-1α under hypoxic conditions; as a result, p300/CBP increases HIF-1α transcriptional activity and cancer cell proliferation." (PMID 35869366, 2022). "ZFP91 takes part in different biological processes, and it promotes cancer development by the control of the NF-кB signaling pathway, FOXA1, HIF-1α, and so on 29,31,44." (PMID 35165513, 2022). "Several studies have demonstrated that acute hypoxia selects for cancer cells with stem cell characteristics, enhancing stem-like cell marker expression, such as OCT4, SOX2, NANOG and MYC, through upregulation of the HIF-1α pathway." (PMID 36224457, 2022). "In this study, we systematically studied HIF1A cofactors in eight cancer cell lines using the computational motif mining tool, SIOMICS, and discovered 201 potential HIF1A cofactors, which included 21 of the 29 known HIF1A cofactors in public databases." (PMID 36347941, 2022). "By inhibiting mTORC1 and activating HIF-1α and NRF2, mitochondria are likely a master regulator of autophagy in cancer cells." (PMID 36292613, 2022). "The most well-understood metabolic changes that occur during cancer progression include alterations in the PI3K/AKT/mTOR pathway, stabilization of HIF-1α, and enhanced expression of MYC genes." (PMID 36519538, 2022). "USP28 is known to be involved in cancer-related pathways by antagonizing FBW7-dependent ubiquitination of several proteins, such as C-MYC, C-JUN, ΔNp63, and Hif-1α." (PMID 36436562, 2022). "Studies are needed to further explore the contribution of miR-630 to prognosis by regulating the expression of HIF-1α and HIF-3α and by modulating cancer hallmarks of HeLa cells." (PMID 36277475, 2022). "Although in clinical studies, until now only few HIF-1α inhibitors have been studied, failure in other cases exerts a major barrier in the development of HIF-1α-targeting anti-cancer therapeutics." (PMID 36014432, 2022). "The gene signatures of HIF-1α, ROS, and HIF-related cancer signals under control versus uninterrupted hypoxia and control versus acute hypoxia were distinct." (PMID 36147561, 2022). "Previous work from our laboratory has established that direct phosphorylation of HIF-1α/HIF-2α by ERK1/2 has a profound effect on HIF-1/HIF-2 activity and cancer cell adaptation to hypoxia." (PMID 35406562, 2022). "Therefore, great possibilities exist that metastatic cancer cells that colonized on the involved lymph nodes may acquire enhanced immune-escape capacities in response to the hypoxia status in the lymph node through the HIF-1α pathway." (PMID 35295999, 2022). "We also compared the levels of HIF1A mRNA in brain (U251), prostate (PC3), and additional breast (MDA-MB-231) cancer cell lines following exposure to normoxia, chronic, and intermittent hypoxia." (PMID 36174675, 2022).